INS (insulin)
Diseases named in the same sentence as INS in open-access papers (continued):
Sharing a sentence is not in itself a finding about the gene and the disease.
atrial fibrillation (91 papers, 2010 to 2026). A disorder characterized by an electrocardiographic finding of a supraventricular arrhythmia characterized by the replacement of consistent P waves by rapid oscillations or fibrillatory waves that vary in size, shape and timing and are accompanied by an irregular ventricular response. "Diagnosed concomitant diseases during hospitalisation included laminitis (n = 2), PPID (n = 1), equine asthma (n = 2), atrial fibrillation (n = 1), mild tricuspid and mitral valve regurgitation (n = 1), and insulin dysregulation (n = 1)." (PMID 41472107, 2025). "In TOPCAT, participants in higher NT-proBNP tertiles were more likely to be older, and exhibited significantly lower body mass index (BMI), lower insulin use, and were more likely to have atrial fibrillation." (PMID 38299345, 2024). "Fluctuating weight in patients with atrial fibrillation (AF) participating in a weight management intervention was associated with increased antihypertensive medication requirements, higher fasting insulin and serum low-density lipoprotein levels, and adverse cardiac remodelling." (PMID 39460984, 2024). "For example, the aryl hydrocarbon receptor nuclear translocator two gene (ARNT2) was identified by GWAS for atrial fibrillation and is a treatment cASE gene in CMs for insulin." (PMID 33988505, 2021). "Other baseline factors associated with hHF during the trial included hepatic impairment, lower eGFR, atrial fibrillation, higher total insulin dose at week 1, prior MI, macular edema, higher A1C, proteinuria and higher systolic blood pressure." (PMID 31729990, 2019). "Participants who required a loop diuretic dose escalation (increase) were more frequently assigned to the placebo group and were more likely to have the following at baseline: NYHA class III/IV symptoms, atrial fibrillation, obstructive sleep apnoea, and treatment with insulin." (PMID 38739118, 2024). "Additional parallels include metabolic syndrome/insulin dysregulation, atrial fibrillation—with spontaneous AF in horses —and tendon injury biology, where the superficial digital flexor tendon mirrors the human Achilles." (PMID 41549528, 2026). "Domestic studies have confirmed that non-insulin-based indicators such as TyG and METS-IR are not only closely related to the occurrence of atrial fibrillation, but can also predict recurrence after ablation and adverse cardiovascular outcomes." (PMID 41584292, 2025). "Tight glucose control with insulin (TGC) is known to reduce inflammation and oxidative stress and may alter atrial metabolism, which, together, could affect atrial fibrillation pathogenesis." (PMID 41987294, 2026). "Our result showed patients with abnormal atrial fibrillation rhythms showed no significant preference for insulin (90/168, 53.6%) versus oral agents (78/168, 46.4%) compared to those with normal rhythms (5/8 insulin, 3/8 oral agents; *p* = 0.55, Fisher's exact test)." (PMID 41383356, 2025). "Several reports of hypoglycemic triggered atrial fibrillations have been reported clinically and information gathered from the Framingham Heart Study suggests insulin resistance does not play a role." (PMID 30534081, 2018).
ischemia (91 papers, 2010 to 2025). A hypoperfusion of the BLOOD through an organ or tissue caused by a PATHOLOGIC CONSTRICTION or obstruction of its BLOOD VESSELS, or an absence of BLOOD CIRCULATION. "It is known that overexpression of TNF-α in normal myocardium directly causes myocardial insulin resistance, aggravating cardiac dysfunction and ventricular dilatation following ischemia." (PMID 37334749, 2023). "Insulin improved cardiac contractility when it was administered preemptively before the “iatrogenic ischemia,” caused by CPB." (PMID 25197648, 2014). "The extensive edema and ischemia also cause decreased insulin production." (PMID 38910717, 2024). "Thus, it is critical to investigate insulin signaling in the brain of comorbid animal models of vascular risk factor such as ischemia in the presence of elevated levels of brain amyloid (adult onset sporadic AD model)." (PMID 29572520, 2018). "Thus, the lower T wave amplitudes observed may reflect underlying changes in potassium, insulin or glucose levels, or silent ischemia." (PMID 39427200, 2024). "Insulin-induced Y97 phosphorylation of Cytc resulted in significant neuroprotection, with a 49% increase in NeuN-positive neurons compared to the ischemia condition alone." (PMID 39941082, 2025). "The ability of insulin to diminish significantly the caspase-3 activity in the hippocampus and frontal cerebral cortex increased in these forebrain regions after ischemia and reperfusion, was also shown." (PMID 39057034, 2024). "Ischemia/hypoxia induces significant translocation of GLUT-4 molecules to the plasma membrane of cardiomyocytes, while the combination of insulin with ischemia triggers an even more pronounced GLUT-4 translocation." (PMID 40376262, 2024). "The protective effect of insulin against AF is only effective when administered before atrial ischemia." (PMID 39541171, 2024). "In the forebrain regions, we studied the effect of ischemia and reperfusion, as well as the administration of insulin and autophagy and apoptosis inhibitors on the intensity of insulin receptor substrate-2 (IRS-2) phosphorylation at Ser731." (PMID 39057034, 2024). "As a result, the use of hormonal regulators with neuroprotective properties, including insulin, is able to compensate for ischemic brain damage, which makes them promising drugs for the treatment of ischemia." (PMID 36834685, 2023). "Improved kidney and liver function, reduced liver steatosis, faster wound healing, insulin efficiency in adipose tissue, and improved heart recovery after ischemia." (PMID 35719120, 2022). "By activating ATP-sensitive K+ channels, H2S lowers blood pressure, protects the heart from ischemia and reperfusion injury, inhibits insulin secretion in pancreatic β cells, and exerts anti-apoptotic, anti-inflammatory, and anti-nociceptive effects." (PMID 35743160, 2022). "Insulin, when given prior to ischemia or at reperfusion, can protect the heart from ischemia-reperfusion injury, as evidenced by the reduced infarct size." (PMID 35563765, 2022). "Recently, a protective effect of intracerebroventricularly administered insulin on the viability of brain neurons in gerbils with global ischemia followed by reperfusion has been shown." (PMID 34769198, 2021). "In this context, in animal models of ischemia, cardioprotection has been achieved by increasing glucose and insulin levels, or by raising the use of endogenous glycogen." (PMID 33673114, 2021). "Still, cardiac and peripheral muscle metabolism are quite different, as are collateral circulation patterns, insulin sensitivity and responses to ischemia." (PMID 34901212, 2021). "Nuak2, also termed SNARK, has been identified as a mediator of insulin-independent glucose transport, specifically regulating exercise- and ischemia-stimulated glucose transport in the heart and contraction-stimulated glucose transport in skeletal muscle." (PMID 33105775, 2020).
ischemia (continued). "At an early stage post-ischemia, enhanced insulin-dependent glucose utilization in cardiomyocytes protects the heart against injury exacerbation." (PMID 32223896, 2020). "Even though SLC2A1 is generally considered to be an insulin-independent glucose transporter, membrane translocation has previously been observed in an insulin-dependent manner during ischemia in cardiomyocytes, similar to the presented culture conditions." (PMID 32656187, 2020). "The clinical literature presents a compelling argument for impaired insulin signaling in the vulnerable brains, such as those developing Alzheimer’s type pathologies or ischemia." (PMID 29572520, 2018). "One of the pathophysiological mechanisms of this phenomenon is the ability of leptin to modulate the cell signaling pathways involved in the insulin, carbohydrate, lipid and energy metabolisms, resulting in increased myocardial injury during ischemia." (PMID 26989445, 2016). "Overexpression of PID1 in human myoblasts results in reduced insulin signaling which has been pointed out as a neuroprotective agent acting mainly against apoptosis, beta amyloid toxicity, oxidative stress, and ischemia." (PMID 27656889, 2016). "Insulin is a potent neuroprotective agent that acts mainly against apoptosis, beta amyloid toxicity, oxidative stress, and ischemia." (PMID 25346723, 2014). "In conclusion, administration of insulin prior to ischemia protected cardiac contractility better than insulin administered during reperfusion." (PMID 25197648, 2014). "Recent acute myocardial ischemia (AMI) model studies have demonstrated reduction in infarct size in isolated rat heart when insulin was administered after ischemia." (PMID 25197648, 2014). "Two mechanisms have been proposed as being involved in insulin protection against ischemia; one by the direct effect of insulin on the brain tissue and the other one by an indirect mechanism in which insulin reduces peripheral glucose levels." (PMID 25346723, 2014). "The overrepresentation of both glucose transporters could be driven by hypoxia-inducible and insulin-mediated pathways, which are activated during ischemia and early reperfusion." (PMID 41009389, 2025). "In addition, reperfusion following ischemia produces endothelial shear stress that enhances vasodilation in response to insulin in mammals, including humans." (PMID 40892466, 2025). "Based on the information provided, we hypothesize that insulin prevents acute atrial ischemia–induced AF." (PMID 39541171, 2024). "Thus, intranasal administration of insulin (before the onset of ischemia and then daily during 7 days of reperfusion) almost completely prevented the death of nerve cells in the hippocampal CA1 region in rats with brain ischemia and reperfusion." (PMID 39057034, 2024). "Insulin pretreatment before ischemia prevented ischemia-induced electrophysiological disorders." (PMID 39541171, 2024). "It was shown that the level of one of the main markers of autophagy, LC3B-II, significantly increased in the hippocampus and frontal cortex under the influence of ischemia and reperfusion, while administration of insulin to rats significantly diminished its level in these brain structures." (PMID 39057034, 2024). "In addition, insulin is also a potent neuroprotective agent, including inhibiting apoptosis, beta amyloid toxicity, oxidative stress and ischemia." (PMID 37599893, 2023). "This time‐sensitivity may partly explain mixed results for glucose‐insulin‐potassium therapy when administered after ischemia onset for acute coronary syndrome." (PMID 36807889, 2023). "As GLUT4 constitutes the most abundant glucose transporter in the heart and translocates from intracellular vesicles to the plasma membrane in response to insulin, ischemia, and hypoxia, it may provide myocardial protection during ischemia." (PMID 36707786, 2023).
ischemia (continued). "Our data indicate that insulin and α-T are able to enhance the protective effects of each other on cortical neurons under conditions of oxidative stress and on the cells of the cerebral cortex of rats with ischemia/reperfusion injury." (PMID 34769198, 2021). "Indeed, oral hypoglycemic and insulin sensitizing agents such as thiazolidinediones, acting as PPARγ agonists, ameliorate glucose utilization also improving cardiac performance after ischemia." (PMID 33673114, 2021). "KATP channels couple the metabolic state of the cell to membrane excitability and play a key role in physiological processes such as insulin secretion in the pancreas, protection of cardiac muscle during ischemia, and hypoxic vasodilation of arterial smooth muscle cells." (PMID 31178728, 2019). "These channels couple the metabolic state of the cell to membrane excitability and play a key role in physiological processes such as insulin secretion in the pancreas, protection of cardiac muscle during ischemia and hypoxic vasodilation of arterial smooth muscle cells." (PMID 31178728, 2019). "Insulin levels with glibenclamide were similar to those observed during hyperinsulinemic clamp studies published by our group, which also showed a neutral effect of insulin on myocardial performance during ischemia." (PMID 27431258, 2016). "We tested the hypothesis that insulin administered prior to ischemia provides better cardioprotection than insulin administration after ischemia." (PMID 25197648, 2014). "Furthermore, in another study, apoptosis of cortical neurons in STZ-induced diabetic rats was controlled with insulin prior to ischemia in the middle cerebral artery." (PMID 24745031, 2014). "In this study, in isolated rat hearts, we tested the hypothesis that insulin administered prior to ischemia provides better cardioprotection than insulin administered after ischemia." (PMID 25197648, 2014). "Preclinical data from animal models indicates that insulin may reduce damage in both global and focal ischemia and in transient global ischemia, insulin has a direct neuroprotective effect on CNS parenchyma." (PMID 22867059, 2012). "Impaired myocardial glucose utilization per unit insulin may detrimentally affect the heart's ability to adapt to conditions, such as ischemia, when the heart's reliance on glucose increases; this is speculative and requires further study." (PMID 22151886, 2011). "Thus, although insulin activated aerobic glycolysis to a large extent (protective effect), it also activated anaerobic glycolysis during ischemia (detrimental effect) due to glycogen loading of the heart before ischemia, as reflected by the increased TOC in the insulin treated hearts." (PMID 38528175, 2024). "We investigated the combined effect of upper leg intermittent ischemia/reperfusion (IIR) and continuous knee-extension exercise on muscle insulin sensitivity regulation." (PMID 40892466, 2025). "Cardiodynamic parameters and coronary flow of diabetic rats treated with NPH insulin, HBOT, or their combination after 20 min of ischemia followed by thirty minutes of reperfusion are shown graphically." (PMID 37760247, 2023). "Noting the protective role of cardiac IRS1, the feasibility of ameliorating cardiac insulin sensitivity and heart injury via maintaining IRS1 following ischemia has been underscored." (PMID 32223896, 2020). "Enhancing glucose uptake has been attempted by insulin infusion called glucose–insulin–potassium (GIK) therapy, which involved exposure to high concentrations of insulin during acute ischemia." (PMID 32612538, 2020). "When the heart was perfused with DG-mixed insulin, amount of released CK and LDH was found to be significantly lowered than normal ischemia reperfusion control." (PMID 21264119, 2010). "Oral and intraperitoneal administration of DG-mixed insulin significantly reduced the CK and LDH levels in perfusate, indicating the preservation of myocardial architecture during ischemia reperfusion." (PMID 21264119, 2010).
ischemia (continued). "Notably, inhibition of phosphoinositide 3-kinases (PI3K) using wortmannin eliminated insulin-triggered GLUT-4 translocation and glucose uptake while leaving those induced by ischemia unaffected, suggesting disparate mechanisms between insulin and ischemia." (PMID 40376262, 2024). "Previous studies have reported that GIK has the potential to alleviate angina pectoris and skeletal muscle pain following ischemia.GIK provides glucose, and the insulin within it facilitates glucose uptake and utilization by cells, thus supplying energy to ischemic tissues." (PMID 38744800, 2024). "While manipulating the oxidative stress response and insulin signaling pathway has similar outcomes in Drosophila hypoxia and the mammalian middle cerebral artery occlusion (MCAO) model of ischemia, effects of Notch pathway manipulation differ between Drosophila and mammals." (PMID 38584778, 2024). "However, it should be noted that, in contrast to neurons, data on the protective effects of insulin and IGF-1 in microglia and oligodendrocytes during ischemia and TBI remain poorly understood." (PMID 36834685, 2023). "Compared with the non-DME group, the DME group had a higher proportion of insulin use and a higher level of serum ischemia-modified albumin and fasting plasma glucose." (PMID 36203780, 2022). "Relative to the HCR phenotype, the LCR phenotype is characterized by decreased endothelial reactivity, increased susceptibility to reperfusion-induced arrhythmias following short, non-infarction ischemia, and increased diet-induced insulin resistance." (PMID 34901212, 2021). "Several factors are reported to induce the translocation of GLUT1 to the plasma membrane, including interleukin 3 (IL-3), nitric oxide, low-density lipoprotein (LDL), insulin, dehydroepiandrosterone (DEHA), ischemia, and the combination of hypoxia and high glucose concentration." (PMID 32962633, 2020). "This, in turn, reestablishes the cardiac insulin signaling pathway (PI3K/Akt/Glut-4/eNOS) thus allowing an optimization of the cardiac metabolism, an improved vasodilator function and preserving cardiac structure during ischemia in the heart." (PMID 28036029, 2016). "However, insulin prevented the decrease in APD and slowing of conduction velocity, resulting in improved electrical conduction homogeneity compared with the control group subjected to 25 minutes of ischemia." (PMID 39541171, 2024). "The ability of intranasally administered insulin and orally administered α-T to normalize the accumulation of lipid peroxidation products (LPO) and prevent oxidative inactivation of Na+,K+-ATPase in the cerebral cortex during ischemia and reperfusion was investigated." (PMID 34769198, 2021). "However, whether spironolactone exerts its protective, anti-ischemia effects, at least in part, through the inhibition of GRK2, and thus restoring cardiac insulin and/or β1AR sensitivity, is currently unknown." (PMID 31447681, 2019). "However, there are no data indicating whether insulin provides protection against acute atrial ischemia or ischemia-induced POAF." (PMID 39541171, 2024). "In rats with ischemia, we have shown an increase in the antioxidant effect of INI when it is co-administered with α-tocopherol, a bioactive component of vitamin E, which may indicate a synergism in the neuroprotective action of insulin and α-tocopherol on neurons." (PMID 36834685, 2023). "In mice with intact insulin signaling, neither IGFBP-1 knockout nor overexpression altered recovery of tissue perfusion after induction of hindlimb ischemia." (PMID 32190801, 2020).